TMEM139 (transmembrane protein 139)
Description:
May be involved in cellular trafficking of proteins such as SLC4A1.
Synonyms: FLJ90586
Tractability: Antibody: UniProt predicts a signal peptide or a membrane-spanning region; the Human Protein Atlas places it where antibodies can reach.
Gene: Protein-coding gene on chromosome 7 (143,279,937 to 143,288,240, forward strand). Ensembl gene ENSG00000178826.
Subcellular location: Membrane
Subcellular location (Human Protein Atlas): Plasma membrane; Focal adhesion sites
Gene Ontology:
Molecular function: protein binding
Cellular component: membrane
Genetic constraint (gnomAD): Loss-of-function variants: 9 observed, 16.02 expected, observed/expected ratio (o/e) 0.56, 90% interval 0.34 to 0.98. The upper end of that interval is the gene's LOEUF score, 0.98, which puts it in group 4 of 6, group 1 being the genes least tolerant of losing a copy. Missense variants: 270 observed, 279.74 expected, observed/expected ratio (o/e) 0.97, 90% interval 0.87 to 1.07. Synonymous variants: 95 observed, 115.15 expected, observed/expected ratio (o/e) 0.82, 90% interval 0.7 to 0.98.
Homologues: Orthologues: chimpanzee TMEM139 (99% identical), macaque GSTK1 (92% identical), dog TMEM139 (71% identical), pig TMEM139 (70% identical), rabbit TMEM139 (68% identical), guinea pig TMEM139 (59% identical), rat Tmem139 (59% identical), mouse Tmem139 (56% identical).
Diseases named in the same sentence as TMEM139 in open-access papers:
TMEM139 is named in the same sentence as 6 diseases in open-access papers, as found by Europe PMC text mining. Sharing a sentence is not in itself a finding about the gene and the disease. The quoted sentences say what the papers report.
ovarian carcinoma (1 paper, 2022). A malignant neoplasm originating from the surface ovarian epithelium. "Transmembrane Protein 139 (TMEM139) has no relevant studies in ovarian cancer." (PMID 35719392, 2022).
pancreatic adenocarcinoma (1 paper, 2023). "Furthermore, TMEM139 gene was identified as the risk prediction marker of pancreatic adenocarcinoma patients by energy metabolism characteristics." (PMID 37174108, 2023).
pancreatic cancer (1 paper, 2023). "Transmembrane protein 139 (TMEM139) has been identified as a novel oncogene and its overexpression has been associated with various types of cancer, including pancreatic cancer." (PMID 37174108, 2023). "In this study, KV significantly downregulated TMEM139 expression in oxaliplatin-resistant pancreatic cancer cells." (PMID 37174108, 2023). "The clinical significance of TMEM139 expression in pancreatic cancer patients was analyzed using the Kaplan−Meier method for overall survival (OS) and relapse-free survival (RFS)." (PMID 37174108, 2023). "Higher levels of TMEM139 expression were associated with a decreased probability for OS and RFS compared with lower levels of TMEM139 expression in patients with pancreatic cancer." (PMID 37174108, 2023). "The expression levels of TMEM139 are negatively correlated with OS and RFS in patients with pancreatic cancer." (PMID 37174108, 2023).
papillary thyroid carcinoma (1 paper, 2022). "In papillary thyroid carcinoma, TMEM139 was a potential independent predictive gene for the recurrence of PTC." (PMID 35719392, 2022).
cancer (2 papers, 2023 to 2026). A tumor composed of atypical neoplastic, often pleomorphic cells that invade other tissues. "(Menispermaceae) inhibited TMEM139 expression (mRNA and protein), which is associated with cancer metastasis, and with the migration and invasion abilities in oxaliplatin-resistant AsPC-1 cells." (PMID 37174108, 2023).
TMEM139 also shares sentences with these, for which no sentence is quoted: tumor (1 paper).